ZNF430 (zinc finger protein 430)
Description:
May be involved in transcriptional regulation.
Synonyms: FLJ13659
Tractability: PROTAC: ubiquitination databases record sites on it.
Gene: Protein-coding gene on chromosome 19 (21,020,614 to 21,060,050, forward strand). Ensembl gene ENSG00000118620.
Subcellular location: Nucleus
Pathways (Reactome):
Gene expression (Transcription): Generic Transcription Pathway
Gene Ontology:
Molecular function: DNA-binding transcription factor activity, RNA polymerase II-specific; RNA polymerase II cis-regulatory region sequence-specific DNA binding
Biological process: substantia nigra development; regulation of DNA-templated transcription; regulation of transcription by RNA polymerase II
Cellular component: nucleus
Genetic constraint (gnomAD): Loss-of-function variants: 32 observed, 52.24 expected, observed/expected ratio (o/e) 0.61, 90% interval 0.46 to 0.82. The upper end of that interval is the gene's LOEUF score, 0.82, which puts it in group 3 of 6, group 1 being the genes least tolerant of losing a copy. Missense variants: 562 observed, 659.48 expected, observed/expected ratio (o/e) 0.85, 90% interval 0.79 to 0.91. Synonymous variants: 209 observed, 226.34 expected, observed/expected ratio (o/e) 0.92, 90% interval 0.82 to 1.04.
Homologues: Orthologues: chimpanzee ZNF430 (98% identical). Paralogues in human: ZNF431 (79% identical), ZNF92 (69% identical), ZNF98 (68% identical), ZNF737 (65% identical), ZNF680 (64% identical), ZNF257 (63% identical), ZNF723 (63% identical), ZNF66 (63% identical), ZNF675 (63% identical), ZNF273 (62% identical), ZNF730 (61% identical), ZNF626 (60% identical), and 6 more.
Diseases named in the same sentence as ZNF430 in open-access papers:
ZNF430 is named in the same sentence as 2 diseases in open-access papers, as found by Europe PMC text mining. Sharing a sentence is not in itself a finding about the gene and the disease. The quoted sentences say what the papers report.
breast tumors (1 paper, 2023). "In their analysis, the genomic region harboring ZNF714 (and other genes, including its closest neighbors: ZNF85, ZNF430, ZNF431, ZNF708) was found to undergo copy number gains in estrogen-negative (ER-) breast tumors as compared to ER+ tumors." (PMID 37958512, 2023).
ZNF430 also shares sentences with these, for which no sentence is quoted: glioma (1 paper).